NALCN (sodium leak channel, non-selective)
Diseases named in the same sentence as NALCN in open-access papers (continued):
Sharing a sentence is not in itself a finding about the gene and the disease.
cancer (continued). "We show that NALCN regulates the release of malignant and normal epithelial cells into the blood, and their trafficking to distant sites where they form metastatic cancers, or apparently normal tissues, respectively." (PMID 36175792, 2022). "The ion channel NALCN regulates cell shedding in mice and enhances metastasis in mouse models of cancer." (PMID 36175792, 2022). "Gene expression of NALCN has been detected in various types of human cancers." (PMID 39766220, 2024). "In addition, studies in mice have shown that deletion of NALCN increases cancer metastasis, while the channel controls CTCs." (PMID 39766220, 2024). "However, lately study has revealed that NALCN is essential for the metastasis of cancer and the transmission of normal cells." (PMID 37152978, 2023). "In this study, we found that NALCN mutation and CNA were found in most cancer types." (PMID 37152978, 2023). "Initially, we examined the relationship between the expression of NALCN and tumor purity to determine whether NALCN plays a role in immune infiltration in pan-cancer, through stromal score, immune score and ESTIMATE score." (PMID 37152978, 2023). "Therefore, it indicated that NALCN expression was strongly related to the degree of TIICs in cancer." (PMID 37152978, 2023). "Significant methylation changes and genetic alteration of NALCN can be observed in many cancers." (PMID 37152978, 2023). "Furthermore, using the TCGA datasets, we estimated NALCN expression in paired cancer and normal tissues." (PMID 37152978, 2023). "Moreover, the relationship between NALCN expression and immune or molecular subtypes in pan-cancer was investigated." (PMID 37152978, 2023). "NALCN protein levels have been found to be higher in most cancers based on IHC analysis." (PMID 37152978, 2023). "MGAT4C, HSPA4L, ZSCAN5A, LOC100505841, and NALCN gene deletions were associated with cancer patients without FCH (p < 0.05), while SMYD3 and NKD2DSV genes were associated with cancer patients with FCH (p < 0.05)." (PMID 33431054, 2021). "Variants in NALCN and UNC80 have been linked to many diseases, including several types of cancer." (PMID 33807947, 2021). "Analysis of genes with non-silent mutations occurring in 2 or more individual cancers identified 16 genes including NALCN (mutated in 4 patients)." (PMID 24904279, 2014). "Moreover, we examined NALCN mRNA expression in CCLE cancer cell lines." (PMID 37152978, 2023). "Consequently, NALCN may serve as a useful indicator of cancer occurrence and play a crucial role in assisting tumor diagnosis." (PMID 37152978, 2023). "It was found that the expression of NALCN was significantly associated with CD8+ T cells infiltration level among 14 cancer types, CD4+ T cells among 17 cancer types, neutrophil among 16 cancer types, DCs among 19 cancer types, macrophages among 19 cancer types, and B cells among 5 cancer types." (PMID 37152978, 2023). "Among ion channels, sodium leak channel non-selective protein (NALCN) seems to be a key player in the processes of cancer metastasis and nonmalignant cell dissemination." (PMID 38473812, 2024). "We identify the sodium leak channel non-selective protein (NALCN) as a key regulator of cancer metastasis and nonmalignant cell dissemination." (PMID 36175792, 2022). "Thus, NALCN regulates cell shedding from solid tissues independent of cancer, divorcing this process from tumorigenesis and unmasking a potential new target for antimetastatic therapies." (PMID 36175792, 2022). "Thus, NALCN regulates cell shedding from solid tissues independent of cancer, divorcing this process from tumorigenesis and unmasking an oncogene-independent metastatic pathway." (PMID 36175792, 2022).
tumor (9 papers, 2011 to 2025). "Low NALCN expression is associated with altered tumor immunity and poor prognosis in GC patients." (PMID 40013144, 2025). "We observed that tumor cells with NALCN knockdown exhibited greater resistance to T cell-mediated cytotoxicity compared to control cells." (PMID 40013144, 2025). "Our results indicated that NALCN expression was significantly lower in GC tissues compared to adjacent non-tumor specimens." (PMID 40013144, 2025). "The objective of this study was to elucidate the critical role of NALCN in GC progression and to characterize immune cell infiltration within the tumor microenvironment." (PMID 40013144, 2025). "Meanwhile, tissue immunofluorescence staining showed that in GC tumor tissues with high NALCN expression, there were more B cells and CD8 T cells clustered, and fewer Th17 cells and Th2 cells clustered." (PMID 40013144, 2025). "Immunofluorescence staining confirmed that B cells and CD8 T cells were more abundant in GC tumor tissues with high NALCN expression, whereas Th17 and Th2 cells were less prevalent." (PMID 40013144, 2025). "NALCN plays a central role in tumor immunity and prognosis and has potential therapeutic and diagnostic aspects." (PMID 39766220, 2024). "NALCN is a sodium leak channel that is frequently involved in tumor evolution and immunity and acts as a tumor suppressor." (PMID 39766220, 2024). "Our results clearly indicate that NALCN is highly methylated in NSCLC tumor tissues, and there was a strong correlation between overexpression or underexpression of its mRNA levels and hypo- or hypermethylation of NALCN in 22 of the tissues examined." (PMID 39766220, 2024). "More studies are required to further investigate the role of NALCN in tumor and the potential therapeutic value of NALCN as an anticancer target." (PMID 37152978, 2023). "From the TCGA cohorts, NALCN genetic alteration status was explored in various tumor samples by the cBioPortal database." (PMID 37152978, 2023). "Enrichment analysis showed that NALCN is closely related to multiple tumor-related signaling pathways." (PMID 37152978, 2023). "In this study, NALCN expression is positively associated with ESTIMATE score in most tumor types, which indicate NALCN expression was related to tumor purity." (PMID 37152978, 2023). "Tumor incidence was unaffected by deletion of NALCN in mouse model, but tumor cell metastasis was markedly increased." (PMID 37152978, 2023). "Enrichment analysis found that NALCN is closely related to multiple tumor-related signaling pathways." (PMID 37152978, 2023). "The results showed NALCN expression was significantly correlated with tumor stage, histological tissue grades, molecular and immune subtypes." (PMID 37152978, 2023). "Circulating tumor cells (CTCs) and metastases are increased significantly through NALCN regulates malignant epithelial cells released into the blood from primary tumors." (PMID 37152978, 2023). "Patients with M0 stage tumors showed only CACNA1H, SLC24A3 and NALCN associated with OS differences, while ATP2A1, ATP13A2, TRPC1, and NALCN proved to be significantly associated with OS in the N1–N3 tumor stage patient subgroup." (PMID 31083561, 2019). "Furthermore, further revealing the potential relationship between NALCN and tumor infiltrating immune cells, as well as the mechanism by which NALCN influences this process." (PMID 40013144, 2025). "However, the potential mechanisms by which NALCN influences tumor development and its immune interactions with GC remain to be elucidated." (PMID 40013144, 2025). "It is suggested that NALCN knockdown may suppress anti-tumor immunity by inhibiting T cell proliferation and promoting tumor development." (PMID 40013144, 2025). "This suggests that NALCN knockdown may suppress anti-tumor immunity by inhibiting T cell function and promoting tumor progression." (PMID 40013144, 2025).
tumor (continued). "Thus, the detection of NALCN promoter methylation in NSCLC tumor tissue provides significant prognostic information for patients with NSCLC." (PMID 39766220, 2024). "However, we strongly believe that the evaluation of NALCN promoter methylation in plasma CTDNA as a non-invasive circulating tumor biomarker should be further investigated in a large and well-defined patient cohort." (PMID 39766220, 2024). "Methylation level of NALCN promoter in tumor and normal tissues was evaluated by UALCAN portal." (PMID 37152978, 2023). "NALCN is enriched in multiple pathways involved in tumor development." (PMID 37152978, 2023). "To further investigate whether NALCN has an effect on the tumor immune microenvironment, we analyzed the correlation between NALCN expression and the level of TIICs from different TCGA cohort tumors, according to TIMER and XCELL algorithms." (PMID 37152978, 2023). "Consequently, NALCN play a critical role in tumor immunity and prognosis, and possesses potential therapeutic and diagnostic implications." (PMID 37152978, 2023). "Loss of NALCN function in our mice caused an abundant and persistent shedding of cells that embed in distant organs, even in the absence of a primary tumor." (PMID 36175792, 2022). "Consequently, NALCN’s influence on the tumor microenvironment may present a potential therapeutic target." (PMID 40013144, 2025). "NALCN deficiency resulted in abundant and persistent cell shedding, even without the primary tumor." (PMID 37152978, 2023). "We found that the mRNA level of NALCN was underexpressed in 12 of 22 (54.5%), NSCLC tissues as the expression of NALCN was reduced in tumor samples comparedto the corresponding adjacent tissue." (PMID 39766220, 2024). "The Hum‐mPLoc 3.0 database predicts that NALCN is in the plasma membrane, and the GEPIA database indicates that NALCN is differentially expressed in CRC tissues and related to tumor prognosis." (PMID 35971319, 2022). "Specifically, NALCN levels were lower in GC tumor tissues and plasma compared to adjacent non-tumor tissues and healthy controls." (PMID 40013144, 2025). "Significant differences in NALCN mRNA expression were observed between tumor and non-tumor tissues in the GSE66229 and GSE65801 datasets." (PMID 40013144, 2025). "Subsequently, IHC staining revealed lower NALCN protein expression in tumor tissue compared to adjacent normal tissues." (PMID 40013144, 2025). "Overall, our results indicated that high levels of NALCN, TRPC1, TRPV2, and CACNA1H could be suggestive of an advanced stage tumor." (PMID 31083561, 2019).
neurological diseases (6 papers, 2017 to 2023). "Neurological disorders are related to NALCN gain-of-function mutations." (PMID 37152978, 2023). "NALCN mutations cause severe developmental and neurological disease." (PMID 37152978, 2023). "Future studies will investigate whether NALCN is associated with other inflammation-related neurological diseases." (PMID 37569281, 2023). "In humans, mutations affecting the NCA channel NALCN cause neurological diseases." (PMID 28968387, 2017). "Thus, PRMT7-mediated NALCN inhibition provides a potential target for the development of therapeutic tools for neurological diseases." (PMID 31601786, 2019).
neurodevelopmental disorder (3 papers, 2021 to 2025). A behavioral and cognitive disorder with onset during the developmental period that involves impaired or aberrant development of intellectual, motor, or social functions. "Interest in the UNC79-UNC80-NALCN pathway has also risen, due to its essential role in the maintenance of respiration, the regulation of circadian rhythms, and because mutations of UNC80 and NALCN cause neurodevelopmental disorders, characterized by development delay and hypotonia." (PMID 33973519, 2021).
psychiatric disorder (3 papers, 2014 to 2025). A disorder characterized by behavioral and/or psychological abnormalities, often accompanied by physical symptoms. "We also discuss how NALCN could represent a therapeutic target to treat a wide variety of human diseases, especially neurological and psychiatric diseases." (PMID 24904279, 2014).
NALCN also shares sentences with these, for which no sentence is quoted: Ataxia (4 papers); autism (4); bipolar disorder (4); Alzheimer disease (3); arthrogryposis (3); cardiac diseases (3); channelopathies (3); pancreatic cancer (3); adenocarcinoma (2); cognitive deficits (2); Infantile Hypotonia (2); infantile neuroaxonal dystrophy (2); metabolic disorders (2); microcephaly (2); movement disorder (2); biotinidase deficiency (1); Bosch-Boonstra-Schaaf optic atrophy syndrome (1); breast invasive carcinoma (1); Central apnea (1); Cerebellar Ataxia (1); cervical squamous cell carcinoma (1); cholangiocarcinoma (1); ciliopathies (1); colon adenocarcinoma (1); COVID-19 (1); endocervical adenocarcinoma (1); endometrial cancer (1); episodic ataxia (1); familial partial lipodystrophy (1); fibrosis (1).
A further 36 diseases each share a sentence with NALCN in 1 paper.